CCR7 (C-C motif chemokine receptor 7)
Diseases named in the same sentence as CCR7 in open-access papers (continued):
Sharing a sentence is not in itself a finding about the gene and the disease.
lymph node metastasis (continued). "Third, CCR7-expressing cells had higher metastatic potential in the lymph node of our heterotopic transplantation mouse model, which was a newly-developed model in the study of lymph node metastasis." (PMID 24766770, 2014). "CCR7-expressing cells had higher metastatic potential in the lymph node of our heterotopic transplantation mouse model, which was a newly-developed model in the study of lymph node metastasis." (PMID 24766770, 2014). "Our findings suggest potential therapeutic strategies for lymph node metastasis, i.e., CCR7 may be a promising biomarker and molecular target for lymph node metastasis." (PMID 24766770, 2014). "Increasing evidence shows that CCR7 may play an important role in directing tumor cells to the draining lymph nodes and contribute to the frequent presence of lymph node metastasis in cancer patients." (PMID 24040244, 2013). "This hypothesis was supported by our findings that the high expression of CCR7 was significantly correlated with the presence of lymph node metastasis and lymphatic invasion." (PMID 24040244, 2013). "A similar study also significantly associated CCR7 expression with lymph node metastasis, while CXCR4 expression was associated but not statistically significant." (PMID 24212639, 2011). "Takanami found that CCR7 may be involved in the development of lymph node metastasis in NSCLC." (PMID 38375207, 2024). "Furthermore, this MNN learning model showed that the level of CCR7 staining could be useful for the objective prognostic evaluation of lymph node metastasis." (PMID 36307918, 2023). "MMP-9 and CCR7 might be beneficial as predictors of lymph node metastasis in LSCC patients." (PMID 37600570, 2023). "Similarly, the downregulation of CCR7 in the bone-seeking variants could also be explained by its role and that of its ligands (CCL19 and CCL21) in lymph node metastasis." (PMID 35158871, 2022). "Surprisingly, CCR7 expression was not linked to lymph node metastases or patient survival." (PMID 35203305, 2022). "Moreover, the CCR7 presence was directly related to the lymph node metastases development in NSCLC." (PMID 32340161, 2020). "T1 patients with CCR7-negative ESCC may be at a low risk of lymph node metastasis; therefore, they could receive less invasive therapy, thereby avoiding radical esophagectomy." (PMID 24766770, 2014). "First, CCR7 could be a candidate that can predict lymph node metastasis." (PMID 24766770, 2014). "utilized IHC to detect the coexpression of CCR7 and MUC1, finding a correlation with lymph node metastasis, regional lymphatic recurrence, and poor prognosis." (PMID 40134607, 2025). "CCR7 significantly regulated the MMP-9 expression and revealed the highest sensitivity to predict the lymph node metastasis in LSCC compared to the MMP-9 protein." (PMID 37600570, 2023). "Tumor samples and normal tissue from 27 patients were analyzed and showed elevated CCR7 and CCL19 for patients with lymph node metastasis." (PMID 35203305, 2022). "Analysis of patient NSCLC tissue concluded that CCR7 and CCL21 levels correlated with VEGF-D expression, lymphatic vessel density, higher clinical stages, lymph node metastasis and decreased patient survival." (PMID 35203305, 2022). "VEGF-C and CCR7 were expressed in approximately half of gastric cancer tissue specimens and co-expression of VEGF-C and CCR7 was a strong predictor of lymph node metastasis." (PMID 35203305, 2022). "In this study, patients who co-expressed CCR7 and MUC1 had increased lymph node metastasis, regional lymphatic recurrence, and lower survival rates." (PMID 33390169, 2021). "Consistent with miR-199a-5p, CCR7 upregulation was also correlated with TNM stage (P < 0.011), Histological grade (P = 0.001), Tumor invasion depth (T) (P < 0.001) and Lymph node metastasis (N) (P < 0.001)." (PMID 27814720, 2016).
lymph node metastasis (continued). "Our study confirmed the importance of CCR7 expression in gastric cancer cells and intratumoral FOXP3+ Tregs as prognostic factors, which were correlated with overall survival and lymph node metastasis in gastric cancer, in line with the previous findings." (PMID 24040244, 2013). "Both CCR7 and FOXP3 expression were significantly correlated with lymph node metastasis (P = 0.009 and 0.024, respectively)." (PMID 24040244, 2013). "It was worth noting that both CCR7 and FOXP3 expression were significantly correlated with lymph node metastasis." (PMID 24040244, 2013). "The CCR7 and VEGF-C mRNA and protein expression levels were significantly higher in patients with cancer types exhibiting lymph node metastasis and a more advanced UICC stage." (PMID 23761820, 2013). "Gastric cancer, which exhibited a co-expression of CCR7 and CXCR4, was revealed to be more likely to include lymph node metastasis." (PMID 23761820, 2013). "The CCR7 and VEGF-C mRNA and protein expression levels were significantly higher in the patients with cancer types exhibiting lymph node metastasis and an advanced International Union Against Cancer (UICC) stage (P<0.05)." (PMID 23761820, 2013). "Researchers hypothesize that the interaction between CCR7 and its corresponding ligand, CC chemokine ligand 21/secondary lymphoid tissue chemokine (CCL21/SLC), may be responsible for the occurrence of lymph node metastasis." (PMID 38225277, 2024). "In a related study, CCR7 expression was observed to be highly variable in 96 colorectal carcinoma patients and although CXCR4 expression was associated with lymph node metastasis, in this study, there was no such correlation for CCR7." (PMID 35203305, 2022). "Since then, CCR7 has been suggested as a biomarker for lymph node metastasis, but, unlike CXCR4, few potential therapies have been developed." (PMID 34298676, 2021). "The high expression of CCR7 was significantly correlated with the AJCC staging and lymph node metastasis of GBC patients, which suggests that CCR7 may promote the development, especially the lymphatic metastasis, of GBC." (PMID 27009073, 2016). "Higher expression (+++ to ++++, strong staining) of CCR7 was associated with AJCC staging (I-IIa vs IIb-IV, P = 0.008 < 0.05) and lymph node metastasis (negative vs positive, P = 0.003 < 0.05), but not with age, gender, histological grade, and classification." (PMID 27009073, 2016). "The expressions of CCR7 and MUC1 were both positively correlated with lymph node metastasis." (PMID 26667143, 2015). "In 64 patients without lymph node metastasis, there were 29 (45.3 %) patients with positive CCR7 expression and 22 (34.4 %) patients with positive MUC1 expression." (PMID 26667143, 2015). "The co-expression of CCR7 and MUC1 was also positively correlated with lymph node metastasis." (PMID 26667143, 2015). "Thus, no apparent relationship between intensity/proportion of CCR7 expression and lymph node metastasis was found." (PMID 24766770, 2014). "However, the expression of the CCR7 and VEGF-C mRNA was significantly correlated with lymph node metastasis and the advanced International Union Against Cancer (UICC) stage (P=0.001 for lymph node metastasis and for staging)." (PMID 23761820, 2013).
lung carcinoma (35 papers, 2010 to 2025). "Lung cancer patients with lymphoid metastatic involvement had higher expression of miR-335 and lower expression of miR-let7a associated with increased CCR7 expression and increased cell migration." (PMID 35203305, 2022). "Specifically, we found that lung cancers deficient in HAI-1 have a loss of CCR7-expressing M1 macrophages." (PMID 34185790, 2021). "The exposure of human H1650 lung carcinoma cells to the CM from siNdst1- or siXylT2-targeted hLEC also resulted in abrogation of CCL21:CCR7 association on the tumor cell surface under similar conditions." (PMID 21172016, 2010). "Furthermore, the enrichment of a CCR7 + DC signature (mregDC) has been linked to improved survival in lung cancer, cutaneous melanoma, breast, and colorectal cancer by analyzing 4,045 human solid tumor transcriptomes from the TCGA73." (PMID 40890106, 2025). "Over CCR7 expression in patients with lung cancer predicted an association with the best diagnosis." (PMID 35874608, 2022). "In addition to cell migratory effects, CCR7 was often associated with increased cancer cell survival including tumors of the breast, gastrointestinal, gynecological, head and neck, lung cancer and leukemia." (PMID 35203305, 2022). "This figure presents a detailed analysis of immune responses and genomic states across different cell types in lung cancer, focusing on three key genes: CCR7, TLR4 and TLR2." (PMID 41319095, 2025). "Intriguingly, despite the conserved expression of co-inhibitory molecules such as PD-L1 in CCR7+ DCs, the expression of the DC activation-associated marker LAMP3 is associated with improved prognosis in breast, lung cancer and metastatic melanoma." (PMID 38267413, 2024). "CCR7 mRNA expression was upregulated (RQ > 1) in two study groups: lung cancer tissue (98%) and macroscopically unchanged lung tissue (100%)." (PMID 35160116, 2022). "It was revealed that CCR7 expression is induced by hypoxia, which enhances the migration and invasion of lung cancer cells." (PMID 35160116, 2022). "CCR7-induced lung cancer cell survival involved upregulation of pro-survival bcl-2 and downregulation of pro-apoptotic bax and caspase-3." (PMID 35203305, 2022). "Conversely, in lung cancer, decreased CCR7 led to decreased NF-κB and decreased TGF-β1, which reduced EMT." (PMID 35203305, 2022). "Here, we found that the CCR7 was expressed by the B and T cells in both blood and lung cancer tissues." (PMID 35069521, 2021). "CCR7 combined with the ligand can promote the metastasis of lung cancer cells by up-regulating the expression of sp1." (PMID 33158173, 2020). "The study of CCL21/CCR7 will have important significance for the prevention and treatment of lung cancer metastasis." (PMID 33158173, 2020). "The correct reference is “Takanami, I., Overexpression of CCR7 mRNA in nonsmall cell lung cancer: Correlation with lymph node metastasis." (PMID 31146450, 2019). "Reference 94 to “Takanami, I., Overexpression of CCR7 mRNA in nonsmall cell lung cancer: Correlation with lymph node metastasis." (PMID 31146450, 2019). "It has been reported that CCL19 and CCR7 are able to inhibit metastasis in lung cancer and ovarian cancer." (PMID 30250188, 2018). "Previous studies indicate that CCR7-mediated signaling required for invasive and pro-survival functions in head and neck cancer cells is mediated by PI3K/AKT pathway, whereas CCR7-mediated cell cycle progression in lung cancer cells utilizes ERK1/2 pathway." (PMID 25744065, 2015). "The data suggested that hypoxia elevates CCR7 and promotes a metastatic phenotype of lung cancer." (PMID 35203305, 2022). "The potential role of SNPs in CCR7-mediated lung cancer responses was investigated." (PMID 35203305, 2022).
lung carcinoma (continued). "Overall, lung cancer metastasis to lymph nodes is dependent upon CCR7/ligand-mediated α4β1-integrin responses and upregulation of the transcription factor, SP1 with resultant activation of heparinase and breakdown of the extracellular matrix, promotion of EMT and metastasis." (PMID 35203305, 2022). "The relevance of CCR7 to lung cancer was determined in a study looking for prognostic genes based on a screen that identified 158 potential candidates that were further analyzed by quantitative reverse transcriptase PCR on malignant samples from 147 NSCLC patients." (PMID 35203305, 2022). "Some studies have also revealed the roles of CXCR4, CXCR5 and CCR7 in lung cancer." (PMID 32896997, 2020). "For instance, a search for chemokine/chemokine receptor system in lung cancer showed that the interaction of CC-chemokine ligand 21 (CCL21) with its receptor CC-chemokine receptor 7 (CCR7) may help protect against tumor cell apoptosis through p-ERK-mediated increase of the Bcl-2/Bax ratio." (PMID 38031087, 2023). "Moreover, 5 year disease-free survival and 5 year overall survival were significantly higher for lung cancer patients with positive expression for all three chemokine receptors compared to controls with CCR7 expression having the highest significance (p < 0.001 for both survival parameters)." (PMID 35203305, 2022). "The discovery of the CC chemokine receptor 7 (CCR7) in the membrane of lung cancer cells suggests that it may be utilized to migrate along the gradient of C-C motif chemokine 19 (CCL19) and chemokine 21 (CCL21) towards the lymph node and subsequently cause lymph node metastasis." (PMID 35160116, 2022). "For example, CCR7 may also be expressed by T cells and certain lung cancer cells." (PMID 25338516, 2015). "Six key immune genes (TLR2, TLR4, CCR7, IL18, TIRAP and FOXP3) showed cell‐type specific expression patterns in the lung cancer microenvironment." (PMID 41319095, 2025). "Compared with PBNs in lung carcinomas patients, increased levels of CCR5, CCR7, CXCR3, and CXCR4 are expressed in TANs, whereas CXCR1 and CXCR2 expression are downregulated." (PMID 41254689, 2025). "Our analysis identified six key immune regulatory genes (TLR2, TLR4, CCR7, IL18, TIRAP and FOXP3) that show differential expression between lung cancer and normal tissues and demonstrate potential prognostic value." (PMID 41319095, 2025). "Two CCR7 SNPs, CCR7 rs3136685 and CCR7 rs17708087, were identified as having an elevated risk of NSCLC compared to the wild-type gene; both CCR7 SNPs are postulated to be histone epigenetic modifiers and may represent patients at particularly high risk of developing lung cancer." (PMID 35203305, 2022). "Different research reported CCR7 as a cancer marker, but its effects on the OS of cancer patients are still unknown because different studies have shown distinguished results even in the same type of tumor in different patients, for example, rectal cancer and lung cancer." (PMID 35874608, 2022). "Lung cancer-derived exosomes inhibit the migration of DCs to lymph nodes by broadly decreasing the C-C/C-X-C chemokine receptors, especially CCR6, CCR7, and CXCR3, on DCs." (PMID 34572829, 2021). "In lung cancer, CCL21/CCR7 triggers tumor cell migration and invasion via the EMT and ERK1/2 signaling pathway, thus providing a potential target for lung cancer treatment." (PMID 33146700, 2020). "Previous results from our laboratory indicated that CCR7 and its ligand CCL21 regulate migration and invasion of lung cancer cells through the ERK1/2 pathway under hypoxic conditions and promote metastasis of lung cancer." (PMID 20569443, 2010). "Furthermore it was revealed that CCR7 is involved in the regulation of cell apoptosis, proliferation, and EMT in lung cancer cells." (PMID 35160116, 2022).
lung carcinoma (continued). "In hypoxia, HIF-1α promotes cell migration and invasion by inducing multiple genes, including the stromal cell-derived factor-1/C-X-C motif chemokine receptor-4 (SDF-1/CXCR-4) axis, C-C motif chemokine receptor 7 (CCR7), and lysyl oxidase (LOX) in lung cancer cells." (PMID 31061665, 2019). "Compared to circulating blood neutrophils, TANs isolated from early-stage human lung cancer exhibited an activated phenotype, characterized by low CD62L and high CD54 expression, along with a distinct chemokine receptor profile including CCR5, CCR7, CXCR3, and CXCR4." (PMID 41254689, 2025). "Contrary to the role of CCR7 on lung cancer proliferation, survival and metastasis to the lymph nodes culminating in reduced survival, some publications suggest that CCR7 is beneficial in lung cancer rather than detrimental." (PMID 35203305, 2022). "CCR7 and CD163 could be used as markers of macrophage polarization in lung cancer microenvironment." (PMID 34367284, 2021). "In addition, the reports showed that the interaction of CCR7 and CCL21 is involved in various physiological processes including the proliferation and metastasis of different types of tumor cells, including breast, pancreatic and lung cancer." (PMID 33158173, 2020). "Besides, CCR7, CST7, GPR143, HDAC5, and IDO1 are also related to lung cancer or the MAPK pathway." (PMID 30972101, 2019).
viral infection (34 papers, 2009 to 2025). "In peripheral blood, CD4+ T cells with low CD27, CD28, and CCR7 expression associate with viral infections and display cytotoxic functions." (PMID 30389931, 2018). "Notably, downregulation of CCR7 expression and reduction of associated chemotaxis during viral infections, have been reported." (PMID 34778050, 2021). "Moreover, the importance of CCR7 in immune cell migration to lymphatics was further emphasized in host defense, wherein CCR7-deficient mice exhibited increased susceptibility to both bacterial and viral infections." (PMID 35140675, 2021). "Here, we identified CCR7 as an important receptor for iMO recruitment from the bone marrow to the brain following virus infection." (PMID 38658802, 2024). "Chemokine CCL19 and its receptor C-C chemokine receptor type 7 (CCR7) axis are involved in the immune response to viral infections." (PMID 36899824, 2023). "During viral infection, antigen uptake by dendritic cells upregulates expression of CCR7, a G protein-coupled chemokine receptor, which drives antigen-presenting cells to lymphoid tissue." (PMID 36420258, 2022). "Chemokine CCL19, together with its receptor CCR7, is one of the most important factors recruiting immune cells into target organ during virus infection." (PMID 35935208, 2022). "It has been shown to enhance resistance to various viral infections in murine models by allowing CCR7+ T cells and dendritic cell to migrate to the spleen and lymph nodes." (PMID 34218330, 2021). "We present and discuss the expression, signaling adaptor proteins and effects of CCL19 and CCR7 as these molecules differentially impact different viral infections and viral life cycles in host homeostatic strategies." (PMID 31632965, 2019). "For this review, we searched CCR7-associated chemokine signaling pathways in the KEGG PATHWAY Database1 and discuss the multiple regulatory mechanisms of CCR7 signaling and the influences on CCR7 functions during viral infections." (PMID 31632965, 2019). "Similar to other GPCRs, CCR7 plays a crucial role in activating or inhibiting downstream signaling adaptors in viral infections through G-protein-promoted secondary messengers, including cAMP, Ca2+, and phosphoinositides." (PMID 31632965, 2019). "CD38, CD161, CD27, CD127 and CCR7 are receptors that are extensively expressed on multiple lymphocyte subsets and have been demonstrated closely related to various diseases, including viral infections, autoimmune diseases and cancers." (PMID 40510360, 2025). "We have searched CCR7-associated chemokine signaling pathways on KEGG PATHWAY Database and discussed the multiple regulatory mechanisms of chemokine signaling and the impact on the downstream function of CCR7 during viral infection." (PMID 35252042, 2022). "Importantly, as CCR7+ effector T cells progress to an exhausted state during viral infection, they downregulate CCR7 expression." (PMID 33708224, 2021). "CCL19 could act as a lymphocyte chemoattractant factor via CCR7 in some virus infections or inflammatory disorders." (PMID 33668643, 2021). "In addition, our investigations showed that virus can mimic the function of CCR7 and promote viral infection and migration infection." (PMID 34218330, 2021). "Expression of CCL19 and its receptor CCR7 during viral infections." (PMID 31632965, 2019). "Hence, we systematically evaluated the contributions of CCL19 and CCR7 expression polymorphisms, signal transduction and CCL19-based adjuvant mechanisms in viral infections." (PMID 31632965, 2019). "In this review, we evaluate the functional efficacies of CCL19 and CCR7 in viral infection and prevention, which may facilitate the development of more potent, durable and safe T cell-based anti-virus pharmaceuticals or vaccines." (PMID 31632965, 2019).